EGFR (epidermal growth factor receptor)
Diseases named in the same sentence as EGFR in open-access papers (continued):
Sharing a sentence is not in itself a finding about the gene and the disease.
tumor (continued). "Numerous mutated genes correlated with tumor therapy response, such as EGFR, KRAS, ARID1A, and SMARCA4." (PMID 36290859, 2022). "In this study, 72 (71.3%) of the 101 patients with multiple lung cancers had EGFR mutations in at least one tumor." (PMID 35740676, 2022). "Overexpression of β-galactoside α-2,6-sialyltransferase, which increases α-2,6 sialylation of EGFR, has been linked to poor prognosis of cancers and has been implicated in promoting tumor cell proliferation and drug resistance in some cancers." (PMID 35955894, 2022). "EGFR is expressed on the surface of normal epithelial cells, while it is often overexpressed in some tumor cells and is associated with metastasis, invasion, and poor prognosis of tumor cells." (PMID 36497453, 2022). "In our patient cohort, the detection of targetable tumor alterations (EGFR mutation and ALK fusion) has led to treatment with EGFR/ALK specific tyrosine kinase inhibitor in all stage IV patients according to the present-day recommendations." (PMID 35108331, 2022). "A pooled analysis of 15 published studies and data from the Cancer Genome Atlas showed that patients with NSCLC harboring EGFR mutations have lower PD-L1 expression in their tumor tissue." (PMID 35742933, 2022). "The ability of the tracer to differentiate between resistance mutation L858R/T790M expressing H1975 and wild-type EGFR expressing H441 xenografts was evaluated in tumor-bearing female BALB/c nu/nu mice." (PMID 35455447, 2022). "Previous studies suggested that the point mutation of EGFR is an important way for tumor cells to develop resistance to several TKIs." (PMID 35814475, 2022). "Treatments of these oncogene-addicted tumours, such as the use of tyrosine kinase inhibitors (TKIs) of mutated epidermal growth factor receptor, have dramatically improved the outcome of patients." (PMID 35456982, 2022). "Univariate analysis of patients with an EGFR mutation in ctDNA showed that the L858R mutation in tumor tissue or ctDNA was a marker of shorter OS and PFS." (PMID 35057806, 2022). "Targeted EGFR therapies often demonstrate toxicity associated with on-target off-tumor target binding." (PMID 35281913, 2022). "Avoidance of EGFR impediments for patients with EGFR wild type/mutated NSCLC is normally characterized by “uninflamed” tumor microenvironment, weak immunogenicity, and immunological tolerance." (PMID 35978836, 2022). "Our results confirmed that T790M mutation is more often detected in patients with a large tumor spreading in the chest and with the long duration of response to first- or second generation of EGFR TKIs." (PMID 35522668, 2022). "Confirmatory IHC showed expression of both ALK and mutation-specific EGFR-L858R protein in the same tumor cells, despite the generally mutually exclusive occurrences of driver mutations in treatment-naïve lung cancers." (PMID 36153311, 2022). "Different subclassifications of NSCLC are identified by specific genetic alterations present in tumours, such as oncogenic driver mutations in the epidermal growth factor receptor (EGFR) gene." (PMID 36010935, 2022). "Perhaps in the future, some AFUs targeting the core fucosylation site can be designed to specifically inhibit tumor progression caused by EGFR." (PMID 36046653, 2022). "The incidence of EGFR Ex20ins mutations in ISP and ISP-associated SNSCC tumours implicates a prominent role for activating EGFR mutations in these diseases and opens up an exciting opportunity for treatment with EGFR targeted therapies." (PMID 35053553, 2022). "Some reports suggest that inhibition of the EGFR pathway can reestablish oxidative metabolism associated with a decrease in glycolytic markers as well as lactate production, limiting fuel for tumor cell proliferation." (PMID 35337178, 2022). "Epidermal growth factor receptor (EGFR) is overexpressed in many tumour types including up to 90% of HNSCC and is linked to poorer prognosis, therapy resistance and locoregional failure." (PMID 36333293, 2022).
tumor (continued). "Increased EGFR protein and mRNA expressions are linked with poor prognosis, tumor growth, metastasis, and resistance to chemotherapy." (PMID 35402265, 2022). "EGFR mutations were discovered in 2004 following the genotyping of tumours from a subset of patients who were highly responsive to first-generation inhibitors erlotinib and gefitinib." (PMID 35681591, 2022). "Although the study results did not lead to the registration of durvalumab, the authors highlighted the fact that in EGFR-mutated patients with ≥25% of tumor cells expressing PD-L1 the activity of durvalumab was visible and further investigation is necessary." (PMID 36291146, 2022). "Overexpression and mutation of the epidermal growth factor receptor (EGFR) are associated with tumor development, and mutant EGFR selectively activates AKT signaling pathways." (PMID 36494703, 2022). "In patients with NSCLC harboring EGFR mutations, heterogeneous pretreatment tumor evolution is closely associated with the rapid development of resistance to EGFR‐TKIs." (PMID 35029047, 2022). "For instance, epidermal growth factor receptor variant III (EGFRvIII) is tumor-specific deletion of a portion of the EGFR gene that causes constitutive activation of the receptor." (PMID 35690784, 2022). "Epidermal growth factor receptor tyrosine kinase inhibitors (EGFR TKIs) are effective in treating patients whose tumours harbor sensitive EGFR mutations." (PMID 35614407, 2022). "More EGFR protein and mRNA expressions are linked with poor prognosis, more tumor growth, metastasis, and resistance to chemotherapy." (PMID 35402265, 2022). "EGFR-associated antibodies and inhibitors have proved to be useful for tumor therapy in basic oncology studies." (PMID 35310032, 2022). "Several studies have demonstrated that the expression levels of EGF and EGFR are associated with tumor progression, metastasis formation, and resistance to treatment." (PMID 35409206, 2022). "During the first-generation EGFR TKI treatment, the EGFR T790M variant appeared, disappeared, and reappeared, indicating spatial and temporal diversity due to competitive evolution between different tumor clones." (PMID 35892510, 2022). "In the current study, all resected tumor specimens had preserved the original activating EGFR mutation." (PMID 36581631, 2022). "The targeted therapies are tailored to the patient based on the specific genetic background of the tumor (e.g., mutation or altered expression of EGFR, KRAS, BRAF, PIK3CA, PTEN, HER2, or gene fusion of ALK, ROS1, RET)." (PMID 35205667, 2022). "Of note, the substantial survival benefit and suppression of tumour growth, observed in sapitinib-treated VilCreER;Apcfl/+;KrasG12D/+;Alk5CA mice, is promising, particularly as the potency of EGFR-targeted therapies rapidly diminishes following Kras mutation." (PMID 36477656, 2022). "In our tumor neoantigen study, neoantigens derived from EGFR mutation were identified in patients with lung cancer and found to be related to the survival of the patients." (PMID 35799264, 2022). "Various types of cancer are known to have oncogenic EGFR alterations, including EGFR overexpression, gene amplification, and tumor-specific mutation." (PMID 35453686, 2022). "EGFR-mutated NSCLC depends on a large quantity of intracellular ATP for tumor progression, so visfatin is critical to the survival of EGFR-mutated NSCLC." (PMID 36429891, 2022). "The pulsatile behavior of tumor-specific mutant clones, detected through mutation monitoring over time on ctDNA, provided a scientific rational for the retreatment with anti-EGFR." (PMID 36230757, 2022). "The potential for EGFR ECD mutations to drive resistance to anti-EGFR antibodies is documented through ctDNA and tumor biopsies." (PMID 35457259, 2022). "In vivo, we tested the sensitivity of EGFR variants to different regimens of EGFR-TKIs by examining changes in the proportion of each variant within the tumor." (PMID 35304574, 2022).
tumor (continued). "Pool analysis of 15 published studies and data from The Cancer Genome Atlas show that patients with NSCLC with EGFR mutations have lower PD-L1 expression in their tumor tissue." (PMID 35132961, 2022). "The effect of RBM10 deficiency on EGFR-mutant NSCLC established in this study sheds light on the role of tumor genetic heterogeneity in the multifaceted evolution of therapeutic resistance." (PMID 35579943, 2022). "During the experiment, we designed three combination strategies involving different administration orders and evaluated their integration effect on tumor cell growth with several NSCLC cell lines harboring distinct EGFR mutation." (PMID 35501907, 2022). "Clinicopathologic characteristics were generally well-balanced between those who did or did not receive GCs in terms of sex, age, smoking history, histology, tumor stage, EGFR mutation status, and extent of resection." (PMID 35402494, 2022). "When tumor tissue from NSCLC patients harbors activating EGFR gene mutations, these can be treated with tyrosine kinase inhibitors (TKIs), such as gefitinib and afatinib." (PMID 36468116, 2022). "This potential tumor-promoting activity was also supported by higher relative variant frequencies (RAFs) of ERBB2ΔEx16 detected in untreated LC patients than in their EGFR TKI-resistant counterparts or in GC patients." (PMID 36686783, 2022). "Previous studies have demonstrated that radiomics can distinguish tumors with EGFR mutations from those with wild-type EGFR and provides a noninvasive and quantified approach to gain insight into tumor heterogeneity." (PMID 36059655, 2022). "We previously found that hyperactivation of the EGFR-AKT pathway was closely linked to the immune escape of tumor cells." (PMID 35440620, 2022). "EGFR-mutated NSCLC has been reported to be more likely to have an uninflamed tumor microenvironment, and PD-1 axis inhibition was once considered a blunt sword in this setting due to its poor effectiveness." (PMID 36159795, 2022). "It is also possible to detect potentially actionable activating genetic abnormalities specific to primary tumours (e.g., EGFR gene mutations or ALK and ROS1 gene rearrangements in patients with NSCLC)." (PMID 35884492, 2022). "In a phase 2 trial, monitoring tumor resistance mutations in blood using liquid biopsies allowed rationally guided subsequent therapy with anti-EGFR antibodies in patients with colorectal cancer." (PMID 35915157, 2022). "We investigated the gene expression profile and the diversity of gene mutations before and after the administration of EGFR-TKI at the tumor microenvironment level." (PMID 36505794, 2022). "The cluster of the patients with advanced-stage, high tumor grade, distant metastasis, and positive EGFR expression represent patients at high risk of death (dead patients)." (PMID 36188649, 2022). "Advances in diagnostic technology have provided various methods to detect EGFR mutations, including circulating tumor DNA (ctDNA) analysis (also called liquid biopsy analysis)." (PMID 35740676, 2022). "sox2 is a typical marker of poor differentiated cells that have been associated with CSC and tumor aggressiveness whose levels are regulated by several pathways including EGFR." (PMID 34012924, 2021). "EGFR inhibition with cetuximab diminishes DNA synthesis and double-strand break repair and therefore can increase tumor susceptibility to PARP inhibitors." (PMID 34557197, 2021). "For EGFR sensitive mutation group containing 233 cases, the P value and R2 value of correlation analysis between tumor diameter and HIF-1α level were 0.056 and 0.469, so we can’t absolutely deny the correlation." (PMID 33441708, 2021).
tumor (continued). "A higher percentage of cancer cells bearing the mutated EGFR gene within the tumor was highly correlated with better responsiveness, longer progression-free survival and overall survival in mutEGFR NSCLC patients." (PMID 33461557, 2021). "Inhibition of JAK1/2 signalling was shown to enhance osimertinib’s potency in EGFR‐driven NSCLC xenograft models, including tumours with the therapy‐resistant EGFR T790M mutation." (PMID 33523587, 2021). "Several types of tumours overexpress the Epidermal Growth Factor Receptor (EGFR) in either wild type or mutated form." (PMID 35052732, 2021). "Here we performed single-cell RNA sequencing (scRNA-seq) of total 125,674 cells from seven stage-I/II LUAD samples harboring EGFR mutations and five tumor-adjacent lung tissues." (PMID 33144684, 2021). "In a recent study, HNSCC tumours collected from patients with MAPK1p.E322K mutation and treated with EGFR inhibitor, conferred heightened sensitivity to erlotinib in vivo and proceeding to patient recruitment in a clinical trial." (PMID 34771633, 2021). "NGS was performed in a clinical trial, and an EGFR K860I missense mutation was detected in her tumor." (PMID 33942527, 2021). "Anti-EGFR therapy was even associated with a detrimental effect in patients with KRAS mutant tumours." (PMID 34253874, 2021). "Overexpression of EGFR has been associated with an unfavorable treatment outcome in several tumor entities including HNSCC." (PMID 34830750, 2021). "When reevaluating 16 cases with low tumor cells that were wild type by Sanger, seven of them presented mutations in the EGFR gene at a frequency of 0.9–10%." (PMID 34571741, 2021). "EGFR elevated signaling due to overexpression, mutations, autocrine stimulation or endocytic alterations can contribute to tumor cell malignancy." (PMID 34298835, 2021). "In what way exactly the mutual existence of ALK and EGFR compound mutations in NSCLC impacts tumor behavior still remains a matter of debate." (PMID 33572278, 2021). "The risk score was evaluated in various subgroups, including age, gender, stage, tumor purity, tumor mutation burden, metastasis status, Ki-67, and EGFR." (PMID 33854546, 2021). "This is easily explained by patient KE-04’s EGFR-del9 mutation, as this features drastically larger tumor proliferation." (PMID 34078405, 2021). "We demonstrate an impact of oxygen deprivation, a crucial trait of the tumor microenvironment, on a receptor kinase system exemplarily using EGFR and the associated PI3K/Akt and Ras-MAPK signaling cascades as well as on the immune effector PD-L1 in HNSCC." (PMID 33718186, 2021). "In the end, we were able to conduct tumor xenograft studies using erlotinib-resistant PC9-ErlR cells expressing the EGFR (T790M) mutation." (PMID 34203709, 2021). "Contrary to EGFR, an abnormal expression of E-cadherin implies a reduction in its intensity, as its complete or partial loss correlates with tumor invasion and metastasis." (PMID 34797831, 2021). "This mutation had also been found in tumor tissue, thus excluding the patient from anti-EGFR therapy." (PMID 34943612, 2021). "In this work, the cytotoxic effects of quercetin and its ability to inhibit tumor growth were examined in TKI-resistant NSCLC cells harboring the EGFR C797S mutation." (PMID 34572484, 2021). "They showed significantly reduced cell proliferation, tumor growth and EGFR-c-Met dimerization caused by SGX523 in the resistant mutation case (L858R-T790M) than the other cases." (PMID 34112110, 2021). "The predictive value of biomarkers, including baseline T790M mutation status and others with a plasma-derived circulating tumor DNA EGFR mutation status, are being explored." (PMID 33916930, 2021). "The PD-L1 expression level and EGFR mutation rate, which are tumor tissue factors, are currently used as predictors in clinical settings." (PMID 34022841, 2021).
tumor (continued). "The patient developed multiple TKI resistance mechanisms: T790M EGFR resistance mutation, detected only on tumor cell-free DNA, squamous cell transformation and MET amplification, both detected on a tumor re-biopsy." (PMID 34178662, 2021). "As compared to healthy donors, the blood of NSCLC patients was also much more enriched in non‐mutated EGFR copies, possibly correlating with the presence of tumor‐derived EVs or vesicles deriving from other cells with an ‘altered/activated’ metabolism." (PMID 33942501, 2021). "The two remaining studies investigated the prediction of EGFR mutation at exons 2–7 (EGFRvIII) and incorporated additional imaging features on their modelling such as location parameters, tumor growth model parameters and the peritumoral heterogeneity index." (PMID 34208595, 2021). "In tumor cells, normal signaling is frequently impaired due to increased expression of or mutations in receptor-tyrosine kinases (RTKs), such as the epidermal growth factor receptor (EGFR) (reviewed in Ref.2)." (PMID 33883672, 2021). "In squamous epithelial cells in head and neck tumours, it has already been shown that EGFR activation via HIF-2α leads to more aggressive tumour growth, which in turn can be associated with increased motility and migration ability." (PMID 34251509, 2021). "In other words, these departments reported fewer EGFR mutation tests (<60% of the eligible patients) than expected for their respective tumor volumes (based on the lower 99.7% CI limit) and the national average of 80.9% in 2017." (PMID 34298851, 2021). "The dominating triggers of EGFR activation in tumor tissues are EGFR gene amplification and point mutations." (PMID 34578147, 2021). "Although these tumors have a well-established dependency on EGFR signaling, there remain questions about the underlying genetic mechanisms necessary for EGFR-driven oncogenesis and the factors that allow tumor cells to escape EGFR dependence." (PMID 34944063, 2021). "These cells possessed the most common mutations present in tumor cells, such as EGFR amplification and PTEN loss, confirming that they came from GSC." (PMID 34361013, 2021). "Patients carried at least one sensitizing EGFR mutation (exon 19 del, L858R) based on tumor biopsy and were receiving TKI therapy at the time of enrollment." (PMID 34692681, 2021). "For instance, captured CTCs can be used for EGFR mutation analysis which will provide a better understanding of the tumour genetic profile similar to ctDNA." (PMID 35127511, 2021). "Afatinib, as well as its first-generation EGFR inhibitor counterparts (erlotinib and gefitinib), is most active against tumours expressing EGFR exon 19 or L858R missense mutations." (PMID 34221011, 2021). "Non-small cell lung cancers (NSCLCs) carrying EGFR mutations are currently managed with TKIs, and tumor progression after treatment has been correlated with both genetic alterations and phenotypic transformations toward a mesenchymal phenotype." (PMID 33498502, 2021). "EGFR is implicated in tumor cell proliferation, angiogenesis, tumor invasion, metastasis, and inhibition of tumor cell apoptosis." (PMID 34804932, 2021). "By combining ICO15K-cBiTE AdV encoding an EGFR-targeting T cell engager with folate receptor α (FR-α)-specific CAR T cells this group aimed at addressing tumor heterogeneity and potential antigen loss." (PMID 33863363, 2021). "In EGFR mutant NSCLC treatment, undergoing a tumor rebiopsy is strongly recommended for the detection of secondary mutations (e.g., EGFR T790M) after disease progression with EGFR‐TKI treatment." (PMID 34622569, 2021).